IMP3 (IMP U3 small nucleolar ribonucleoprotein 3)
Diseases named in the same sentence as IMP3 in open-access papers (continued):
Sharing a sentence is not in itself a finding about the gene and the disease.
ovarian epithelial tumor (1 paper, 2023). A benign, borderline, or malignant tumor that originates from the surface epithelium of the ovary. "The results of our study suggest only a limited value of IMP2 and IMP3 for the differential diagnosis of ovarian epithelial tumors." (PMID 36740684, 2023). "We did not confirm the prognostic significance of IMP3 expression in ovarian epithelial tumors, with the exception of LGSC, where negative cases were associated with longer RFS." (PMID 36740684, 2023).
ovarian mucinous tumors (1 paper, 2023). "We identified only three studies focusing on IMP3 expression in ovarian mucinous tumors, two of which included MC only." (PMID 36740684, 2023). "Another study on 250 ovarian mucinous tumors found any extent of IMP3 expression in 12% of benign tumors, 91% of MBT, and 100% of MC." (PMID 36740684, 2023).
ovarian tumors (1 paper, 2023). "Although the expression of IMP3 showed statistically significant differences between some tumor types in our study, the value for differential diagnosis of ovarian tumors seems to be rather limited." (PMID 36740684, 2023). "Concerning IMP3 expression in ovarian tumors, the published literature provides less clear evidence." (PMID 36740684, 2023). "We studied a large cohort of ovarian tumors including HGSC, LGSC, CCC, EC, MC, mucinous borderline tumor (MBT) and micropapillary variant of serous borderline tumor (mSBT) with the aim to assess the value of IMP2 and IMP3 for the differential diagnosis." (PMID 36740684, 2023). "We further investigated the prognostic significance of IMP3 expression in ovarian tumors." (PMID 36740684, 2023). "Most studies of IMP3 and IMP2 expression in ovarian tumors have focused on its prognostic importance, but the results are not conclusive." (PMID 36740684, 2023). "We examined a large cohort of ovarian tumors with the aim to assess the value of IMP2 and IMP3 for differential diagnosis, and to assess their prognostic significance." (PMID 36740684, 2023).
papillary adenocarcinoma (1 paper, 2021). A morphologic variant of adenocarcinoma. "The mechanism underlying such a high value is unclear; however, the presence of papillary adenocarcinoma invading into the sphincter of Oddi could be associated with a sudden increase in the IMP3-positive cell rate." (PMID 34006250, 2021). "The IMP3-positive cell rate has been associated with a poor prognosis in other cancer types; thus, the presence of a high IMP3-positive cell rate could be a factor contributing to poor prognosis in patients with papillary adenocarcinoma." (PMID 34006250, 2021).
papillary carcinoma (1 paper, 2021). A malignant epithelial neoplasm characterized by a papillary growth pattern. "In conclusion, a high IMP3-positive cell rate was found to be a predictor contributing to the poor prognosis of patients with papillary carcinoma." (PMID 34006250, 2021).
pituitary tumor (1 paper, 2012). A benign or malignant neoplasm affecting the pituitary gland. "However, IMP3 expression has been correlated with increased tumor aggressiveness and reduced overall survival in pituitary tumors." (PMID 22280838, 2012).
salivary gland tumors (1 paper, 2020). "In this work, the diagnostic performance of the immunohistochemical markers was as follows: Sensitivity of IMP3 in diagnosing studied salivary gland tumors was 68.2%, the specificity 75%, the PPV 88.2%, NPV 46.1%, and diagnostic accuracy 70%." (PMID 32692399, 2020). "There was a statistically significant relationship between all cases of salivary gland tumors and IMP3 immunostaining (P =0.03)." (PMID 32692399, 2020). "There was a statistically significant relationship between salivary gland tumors and IMP3 immunostaining (P =0.03)." (PMID 32692399, 2020). "The aim of this work was to evaluate the role and sensitivity of immunohistochemical expressions of IMP3 versus DOG1 and p63 (myoepithelial marker) in the diagnosis of salivary gland tumors." (PMID 32692399, 2020).
squamous cell carcinoma of the skin (1 paper, 2023). "Until now, there have been no data about IMP3 expression and clinical outcome for high-risk localisation of squamous cell carcinoma of the skin (cSCC)." (PMID 37627115, 2023).
testicular tumors (1 paper, 2025). "In addition, the presence of diffuse IMP3 protein expression in the retroperitoneal and testicular tumors of this postpubertal patient suggests malignancy in both." (PMID 40071092, 2025).
urachal adenocarcinomas (1 paper, 2018).
tumor (74 papers, 2007 to 2026). "IMP3, normally expressed during embryogenesis, is aberrantly re-expressed in malignancies and linked to tumour progression and poor outcomes." (PMID 41959982, 2026). "IMP3 expression was strongly associated with higher histological grade, larger tumor size, and stromal atypia (p < 0.05)." (PMID 41753301, 2026). "IMP3 is frequently expressed in many different tumour types and has typically been associated with aggressive tumour features." (PMID 37024466, 2023). "Numerous studies have identified that IMP3 tends to promote tumour cell proliferation, migration and most often associates with poor prognosis." (PMID 35315195, 2022). "Our results did not confirm the statistically significant association of sex, age groups and tumor size with IMP3." (PMID 34035433, 2021). "IMP3 protein was expressed higher in the tumour tissues compared to the benign tissues and associated with the tumour stage, tumour grade and prognosis of BC." (PMID 34187252, 2021). "IMP3 is an oncofetal protein since its re-expression correlates with poor prognosis for tumor patients, and studies on IMP3 have mostly focused on its association with the aggressive behavior of many tumors." (PMID 34154626, 2021). "Increased expression of IMP3 is associated with aggressive behavior of different tumor types, advanced clinical stage, distant metastasis, and shorter overall survival (OS)." (PMID 32049813, 2020). "IMP3 has been associated with advanced stage in patients with adenocarcinoma, playing an important role in tumor invasion." (PMID 31450665, 2019). "The hepatocyte growth factor receptor c-Met and the insulin-like growth factor II mRNA-binding protein 3 (IMP3) are linked with tumor invasion." (PMID 31208114, 2019). "Research on IMP3 largely focused on its association with many cancer-related tumor entities, since its re-expression correlates with a poor prognosis for patients, classifying IMP3 as a tumor marker." (PMID 31118463, 2019). "Previous studies examining other cancer types have implicated IMP3 in the regulation of several cellular functions that are characteristic of tumour cells." (PMID 25886367, 2015). "The IMP3-positive tumors were significantly associated with deeper tumor invasion and lymph node metastases compared with the IMP3-negative tumors (P=0.0001 and P=0.026, respectively)." (PMID 25295085, 2014). "Positive IMP3 expression was significantly associated with pathological factors associated with tumor progression [pT, pN and pathological stage (pStage)]." (PMID 25295085, 2014). "Similar associations have been demonstrated between IMP3 expression and older age, larger tumor size, deep tumour invasion and lymph node metastasis." (PMID 24137402, 2013). "Additionally, our study demonstrated an association between IMP3 expression and high-grade tumors, highlighting the role of this marker in distinguishing more aggressive neoplasms." (PMID 39176196, 2024). "This predisposes the protein IMP3 as a tumour marker for oncology decision-making." (PMID 37627115, 2023). "IMP3 overexpression was associated with tumor stage and metastasis (p < 0.05)." (PMID 34154626, 2021). "Furthermore, we analyzed the association of IMP3 protein expression with the clinical and pathological features of the tumor." (PMID 34503117, 2021). "In addition to the expression of IMP3, tumor multiplicity is also a risk factor affecting disease-free survival, and tumor stage T1 (relative to stage Ta) is an unfavorable prognostic factor of progression-free survival and metastasis-free survival." (PMID 31277094, 2019). "We found that IMP-3 protein was significantly associated with tumor thickness and stage II-III." (PMID 26796627, 2016). "In the last few years IMP3, member of insulin-like growth factor II mRNA binding protein family, was investigated in different malignant neoplasms because its overexpression is generally associated with aggressive and advanced tumours." (PMID 23190601, 2012).
tumor (continued). "Nevertheless, other independent factors with a potential influence on survival that have recently been discussed could be considered, e.g. an overexpression of MTA3 gene in NSCLC as a risk factor on survival or an overexpression of IMP3 as a predictor of aggressive tumor behavior." (PMID 24593867, 2014). "Our results demonstrate that m6A sites in the 3′UTR of IGFBP3 play a key role in recruiting and binding IMP3, which is involved in gene regulation and modulation of tumour cell proliferation." (PMID 40621649, 2025). "The results demonstrated that the tumor growth and tumor weight were significantly decreased in IMP3-knockdown cells as compared to controls." (PMID 38271139, 2024). "The insulin-like growth factor II mRNA binding protein 3 (IMP3) is a fetal oncoprotein involved in tumor cell proliferation, adhesion, and invasion." (PMID 39334193, 2024). "In association between IMP3 and KI67, an important marker of cell proliferation and more aggressive neoplasias, was also observed." (PMID 39176196, 2024). "High levels of IMP3 are often found in advanced stages of CRC and are linked to increased tumor invasiveness, metastasis, and poorer overall survival rates." (PMID 39328205, 2024). "Regarding CRC tumour stage, a statistically significant increase of IMP3 expression was detected in patients belong to 1, 2, 3 and 4 stage of the disease." (PMID 37024466, 2023). "The EC group showed intermediate levels of IMP3 expression compared to the other tumor types (39% positive cases, 30% cases with expression in > 50% of tumor cells)." (PMID 36740684, 2023). "The in vivo inhibition of IMP3 with a specific AS reduced tumour volume and paralleled by decreased IMP3 protein expression in the tumour mass." (PMID 37024466, 2023). "Firstly, we have examined IMP3 protein expression in tumour and control mucosa of CRC patients of our cohort by Western blotting and immunohistochemistry." (PMID 37024466, 2023). "The results of our study showed high IMP2 expression (of both clones) in all tumor types, which was higher compared to IMP3 expression." (PMID 36740684, 2023). "Lastly, IMP3 expression can also be used to identify aggressive tumours early on and to adjust the patients’ follow-up care." (PMID 37627115, 2023). "Future studies should also evaluate outcome differences when IMP3 expression is studied in the primarius tumours or in the LNMs." (PMID 37627115, 2023). "Nevertheless, it also shows that IMP3 seems to play a role in many tumour entities with regard to metastasis." (PMID 37627115, 2023). "If two patients had the same tumour stage, but different IMP3 expression levels, the patient with the higher IMP3 expression had a worse prognosis." (PMID 37627115, 2023). "For example, IMP3 participates in RNA trafficking and stabilization which promotes cell proliferation, migration in tumour progression and metastasis." (PMID 35315195, 2022). "The area under curve for ROC curve was 64.3% (95% CI: 46.8% and 81.7%) indicating that IMP3 expression intensity is capable of differentiating these two neoplasms." (PMID 36577979, 2022). "The area under the curve for ROC curve was 75.4 (95% CI: 0.624 and 0.883) indicating that the IMP3 expression intensity is capable of differentiating these two neoplasms." (PMID 36577979, 2022). "Ectopic expression of IMP3 in cancer correlates with adverse outcomes (e.g., higher tumor grade in bladder carcinoma, metastasis and poor survival in esophageal adenocarcinoma)." (PMID 35892887, 2022). "In our analysis, EIF4EBP1, IMP3, ATF3, SEC11A and SHC1 also exhibited different expression between BC and non-tumour samples, and were significantly associated with the tumour type, invasive progression, or tumour grade (SupplementaryFigure S2)." (PMID 34187252, 2021).
tumor (continued). "On the other hand, a higher percentage of tumor cells showed IMP3 expression of high intensity among the third group of IP-associated SCC." (PMID 33680717, 2021). "IMP3 overexpression occurs in various important cancer types including HNSCC and is linked to aggressive tumor features." (PMID 34503117, 2021). "Immunohistochemical staining for IMP3 has been reported to correlate with tumor invasion and prognosis in some neoplasms." (PMID 34006250, 2021). "In this study, IMP3 staining was expected to be an effective marker for determining the correlation with tumor invasion and malignancy in PT." (PMID 34006250, 2021). "According to univariate analysis, disease progression to regional lymph nodes (p = 0.014; HR = 4.44), poor tumor differentiation (p = 0.046; HR = 2.541), and tumors with higher IMP3 expression (p = 0.038; HR = 3.509) had a significant impact on patients’ DSS." (PMID 34503117, 2021). "Prognostic value of IMP3 was investigated in relation to age, gender, histological type of tumor, degree of differentiation, vascular invasion, duration of overall survival (OS) and progression free survival (PFS)." (PMID 34035433, 2021). "We proved that tumors that spread to regional lymph nodes of the neck had a statistically significant higher expression of IMP3 protein, compared to those in which the tumor was restricted to the larynx only." (PMID 34503117, 2021). "In these studies, IMP3 was reported to be diffusely expressed in the entire tumor; therefore, it was useful for analyzing small specimens obtained by EUS–FNA." (PMID 34446759, 2021). "Statistical significance was found regarding the IMP3 expression and tumor size, clinical stage, and basal morphology (P = .039, P = .034, P < .001, respectively." (PMID 32049813, 2020). "Positive IMP3 expression was connected with larger size of tumor, higher clinical stage, and basal morphology (P = .039, P = .034, P < .001)." (PMID 32049813, 2020). "Some molecules involved in mRNA binding, such as insulin-like growth factor II mRNA-binding protein 3 (IMP3), has been demonstrated to promote tumor invasion and predicts early recurrence and poor prognosis in LIHC." (PMID 32191631, 2020). "Multinomial analysis revealed that significant predictors for OS were tumor size (RR = 1.60, P = .022) and IMP3 (RR = 2.67, P = .001)." (PMID 32049813, 2020). "Regarding DFS, statistically significant predictors were tumor size (RR = 1.64, P = .016), clinical stage (RR = 1.25, P = .049), and IMP3 staining (RR = 2.84, P = .001)." (PMID 32049813, 2020). "Compared to parental GL261, each cell line inhibited IFN-γ production by Imp3 neoantigen-specific tumor infiltrating lymphocytes by over 50%." (PMID 32493985, 2020). "In contrast, little relationship was seen between IMP3 expression and patient age (P = .476), gender (P = .508), tumor size (P = .326), tumor multiplicity (P = .810), and smoking history (P = .556)." (PMID 31277094, 2019). "The author states that the increased expression of IGF2 and IMP3 can promote tumor angiogenetic processes." (PMID 28439237, 2017). "We have previously demonstrated that high IMP3 GBM tumors are highly migratory/ invasive as seen by the presence of IMP3 positive tumors cells in tumor infiltrating front, perivascular and subpial regions." (PMID 28465487, 2017). "In conclusion, we demonstrated that tumor stage and IMP3 expression are prognostic indicator in ovarian CCC." (PMID 26837693, 2016). "Further research is required to elucidate additional target RNAs that this RNA-binding protein can regulate and to ultimately develop an inhibitor for IMP3 that prevents its impacts on tumor cells." (PMID 26982091, 2016). "Given the results of our study, it is likely that the role of IMP3 in facilitating metastatic potential is more pronounced in DPC4/Smad4-negative tumour cells." (PMID 25886367, 2015). "The RT-qPCR data confirmed increased levels of IMP3 mRNA expression in the NSCLC samples compared with the adjacent non-tumor tissues." (PMID 25789070, 2015).